ENSG00000279284 ( gene)
Diseases named in the same sentence as ENSG00000279284 in open-access papers (continued):
Sharing a sentence is not in itself a finding about the gene and the disease.
prostate carcinoma (24 papers, 2007 to 2025). A carcinoma that arises from epithelial cells of the prostate gland. "NKX3-1 is a well known tumor suppression gene, whose decreased expression has been associated with prostate cancer." (PMID 32986714, 2020). "In addition, treatment of MM cells with GSK2606414 resulted in the upregulation of HERPUD1 gene expression, which is an ER stress responsive gene that was previously connected to reduced tumor-associated expression in prostate cancer cells." (PMID 33028016, 2020). "PMEPA1 is an androgen-responsive gene initially studied in the context of prostate cancer androgen-regulated gene networks." (PMID 40244296, 2025). "Cluster B included PTEN, a common mutation in mCRPC, and MSH6, a mismatch repair gene seen in 1% of prostate cancer cases." (PMID 38050021, 2023). "Consistently, it has been revealed that SPOP serves as a tumor repressor gene in gastric, colorectal, and prostate cancers." (PMID 35461336, 2022). "Zn finger protein ZNF185 is a LIM domain gene the expression of which is downregulated in several epithelial cancers including prostate cancer." (PMID 36551962, 2022). "RNF7, an apoptosis-sensitive gene, has been shown in several previous studies to play an important role in the development and progression of tumors such as prostate cancer and lung cancer." (PMID 33414811, 2020). "It encodes a mitochondrial enzyme that can protect cell from oxidative damage, and has been known as a tumor suppressor gene in human prostate cancer." (PMID 30367578, 2018). "Overexpression of GPX3 in prostate cancer cell lines seemed to restrain tumor growth and metastasis through downregulation of c-met, a receptor tyrosine tumor transforming gene involved in a variety of cellular processes." (PMID 25970749, 2015). "We have shown that OGR1 functions as a tumor metastasis suppressor gene when it is over-expressed in human prostate cancer cells in vivo." (PMID 19479052, 2009). "TMEFF2 codifies an androgen-regulated transmembrane protein, normally restricted to the brain and prostate tissues, initially described as a tumor suppressor gene for its inhibition of cell growth and hypermethylated status in several tumors, including prostate carcinomas." (PMID 25595908, 2015). "Consequently we propose that zinc is a tumor-suppressor agent; and Zip1, along with Zip2 and Zip3, is a tumor suppressor gene in prostate cancer." (PMID 17550612, 2007). "Therefore, we hypothesized that PLZF acts as the tumor-suppressor gene to improve the poor prognosis in prostate cancer patients." (PMID 32349303, 2020). "We determined whether FOXD1 is a hypoxia-related gene, and explored the roles of FOXD1 in prostate cancer cell growth and glycolysis." (PMID 41214670, 2025). "We also conclude that VPA has differential effects on the metastasis suppressor gene and invasion ability between non-metastatic and metastatic prostate cancer cells." (PMID 26692161, 2015). "Indeed, MT3 has been considered for a long time as a non metal-inducible gene in normal astrocytes and neurons cultures, but recently Wei and co-workers showed MT3 induction after zinc treatment in prostate cancer cells." (PMID 20885975, 2010).
glioma (22 papers, 2010 to 2024). A benign or malignant brain and spinal cord tumor that arises from glial cells (astrocytes, oligodendrocytes, ependymal cells). "miR-204 has been reported to act as a tumor suppressor gene in various malignancies, including glioma." (PMID 38680092, 2024). "In summary, LARP4B is a tumor-suppressor gene of glioma; the potential mechanisms involved, however, remain to be probed further." (PMID 36552760, 2022). "MiR-330-5p has been confirmed to be a tumor-suppressor gene in many cancers including papillary thyroid cancer, glioma, oesophageal adenocarcinoma and melanoma." (PMID 33176280, 2020). "ERCC1 is a DNA repair gene whose protein product plays an important role in nucleotide excision repair; both its protein and mRNA expression is reduced in colon cancer and glioma." (PMID 27410681, 2016). "In another study, sensitization of glioma cells to TMZ by JNK inhibitors was observed in MGMT expressing cells due to an impact of JNK on the basal expression of this DNA repair gene." (PMID 26418950, 2015). "Along with the role of Cx43 as a channel in glioma, studies show that Cx43 can act as a tumor suppressor gene, as well." (PMID 24904426, 2014). "The downregulation of miR-23a expression in glioma cell lines suggests that miR-23a may be a tumor suppressor gene of oral squamous cell carcinoma." (PMID 35342401, 2022). "Our previous study showed that miR-204-5p is a tumor suppressor gene in glioma." (PMID 32489472, 2020). "Meanwhile, the present study provides evidence that DACT2 as a tumor suppressor gene could inhibit growth and induce apoptosis of glioma cells by suppressing YAP through Wnt/β-catenin signaling pathway." (PMID 28796248, 2017). "However, in glioma and some other cancers, miR-146b-5p expression is downregulated and acts as an tumor suppressor gene." (PMID 27166258, 2016). "TRPM3 may play a vital role as a tumor suppressor gene in glioma." (PMID 38680092, 2024). "Collectively, although these investigations showed that NDRG1 might be suggested to have the potential of a tumor suppressor gene in glioma, several factors might lead to poor prognosis and reduced OS, such as tumor environment (e.g., hypoxia, stress condition) and genotoxic changes by chemotherapy." (PMID 35448004, 2022). "Therefore, miR-450a-5p may serve as a tumor suppressor gene in glioma." (PMID 32820249, 2020). "Since YAP is a well-known tumor-promoting gene in gliomas, we speculate that SU4312 may repress the proliferation, invasion and migration of gliomas by inhibiting the transcription and expression of YAP." (PMID 36013004, 2022).
lung carcinoma (22 papers, 2013 to 2026). "Multiple studies have indicated that GPRC5A serves as an important tumor suppressor gene in lung cancer." (PMID 38634049, 2024). "Silencing SLIT3 expression enhanced cell proliferation and migration, indicating potential characteristics of a tumor suppressor gene of SLIT3 in non–small-cell lung cancer (NSCLC)." (PMID 39479352, 2024). "In view of our data indicating that Uc.339 behaves as a "growth metastasis promoting gene" in lung cancer, we next tried to determine the possible mechanism of this phenotype." (PMID 35399708, 2022). "Cell experiments confirmed the role of TRIM58 as a tumor suppressor gene in lung cancer and overexpression of TRIM58 inhibited the malignant phenotype of tumors." (PMID 34434284, 2021). "Our analyses identified AP1S3 as a second clinically relevant AP-1 adaptor gene in lung cancer." (PMID 41438582, 2026). "Our correlation analysis revealed that the correlation between IL22RA1 with macrophage was significantly obvious suggesting that the IL22RA1 might be an immune-related gene in lung carcinoma." (PMID 34040139, 2021). "In summary, our study demonstrates that FTX may function as a tumour suppressor gene and regulate lung cancer development through acting as a sponge of miR‐200a‐3p to promote FOXA2 expression." (PMID 32176463, 2020). "However, a recent study unveiled KDM6A as an important tumor suppressor gene in lung cancer with evidence gained from human lung cancer specimens and transgenic NSCLC mouse models." (PMID 30002791, 2018). "These indicated that miR-21-5p and miR-196a-5p might serve as oncogene, and miR-218-5p might act as tumor suppressor gene in lung cancer." (PMID 27247934, 2016). "Because previous studies have shown that MR expression is down regulated in both colorectal and lung cancers, it has been suggested that MR may act as a tumor-suppressor gene." (PMID 23555666, 2013). "We demonstrated that PARK2 may be a bona fide tumor suppressor gene that may be responsible for the development of progression lung cancer with COPD, suggesting PARK2 as a potential target to reduce the risk of COPD and lung cancer." (PMID 27329585, 2016). "Therefore, it is suggested that it might act as a tumor suppressor gene for lung cancer." (PMID 36067196, 2022). "The classical tumor EMT inducer TGF-β further confirmed that TAp63α acts as a tumor suppressor gene in lung cancer development and the inhibition of TAp63α triggered the EMT process in lung cancer." (PMID 33748140, 2021). "Previous studies have indicated that CTNNBIP1 may be a tumor suppressor gene, but its anti-migration properties have not yet been reported for human lung cancers." (PMID 31766223, 2019).
ovarian carcinoma (21 papers, 2009 to 2024). A malignant neoplasm originating from the surface ovarian epithelium. "Furthermore, miR-1-3p could be a tumour suppressor gene to differentiate between endometriosis and ovarian cancer while monitoring the risk of malignant transformation from endometriosis to ovarian cancer." (PMID 39457531, 2024). "A growing body of evidence has illuminated that LSAMP was inactivated and loss of expression due to DNA methylation modifications and acted as a tumor suppressor gene in osteosarcoma, acute myeloid leukemia, renal carcinoma and ovarian carcinoma." (PMID 35524253, 2022). "In turn, the miR-15 and miR-16 were down-regulated in ovarian cancer tissues, whereas miR-31 was expressed at low levels in serous ovarian cancer cells and tissues, suggesting its role as a tumor suppressor gene of ovarian cancer." (PMID 31035447, 2019). "PTCH2 is a membrane receptor, member of the Hedgehog signaling pathway, and has been associated with proliferation-related disorders such as endometriosis and ovarian carcinoma, playing a role as a tumor suppressor gene." (PMID 29118976, 2017). "Taken together, our data demonstrate that KLF4 functions as a tumor suppressor gene in ovarian cancer cells by inhibiting TGFβ-induced EMT." (PMID 25137052, 2014). "In summary, we have identified a number of Notch proteins as key transcriptional targets of the breast/ovarian cancer tumour suppressor gene BRCA1." (PMID 23863842, 2013). "Our results support a role for SFRP4 as a tumor suppressor gene in ovarian cancers via inhibition of the Wnt signaling pathway." (PMID 22363760, 2012). "Dabholkar and colleagues found that the mRNA level of some DNA repair gene was significantly increased in platinum-resistant ovarian carcinoma, indicating that the level of DNA repair gene expression correlates with the response to platinum-based chemotherapy." (PMID 19563645, 2009). "RPS6KA2 was also identified as a cancer suppressor gene in epithelial ovarian cancer." (PMID 34676211, 2021). "The results indicated that miR-30b-3p was a tumor suppressor gene for ovarian cancer." (PMID 32156314, 2020). "We propose a model in which MYPT1 acts as a tumor suppressor gene in ovarian cancer." (PMID 31926547, 2020).
melanoma (20 papers, 2004 to 2025). A malignant, usually aggressive tumor composed of atypical, neoplastic melanocytes. "The 10q24.33 region containing OBFC1, a known telomere maintenance gene, has been implicated in lymphocytic leukemia, melanoma, and kidney, ovarian, and thyroid cancers." (PMID 33579919, 2021). "In combination, evidence suggests that RYBP act as tumour suppressor gene in different solid tumours but as an oncogene in lymphoma and melanoma; however, the precise underlying mechanisms of these opposing function remain to be clarified." (PMID 29383875, 2018). "In our study, we found that miR-10a-5p was obviously diminished in melanoma tissues by bioinformatics method, showing that miR-10a-5p serves as a tumor suppressor gene in melanoma." (PMID 34424910, 2021). "While TFG was supposed to be a tumor-suppressive gene in melanoma, its role in melanoma has been understudied." (PMID 33066509, 2020). "Bcl-2 is an anti-apoptotic gene and has been involved in many cancers such as melanoma, breast, lung, and liver carcinomas." (PMID 31684176, 2019). "Melanoma differentiation associated gene-7 (MDA-7), also known as interleukin (IL)-24, is a tumour suppressor gene associated with differentiation, growth and apoptosis." (PMID 20735832, 2010). "Collectively, this work discovered that UTRN could act as a tumor suppressor gene in melanoma and serve as a prognostic factor." (PMID 33632212, 2021). "miRNA-23b-3p was shown to be a tumour suppressor gene in melanoma." (PMID 32993558, 2020). "Furthermore, RYBP has also been shown to act as tumour suppressor gene in different solid tumours, but as an oncogene in lymphoma and melanoma." (PMID 29383875, 2018). "In addition, we have identified that MECOM, a novel, central epigenetic regulatory gene, and TET2/IDH1, critical regulators of DNA demethylation, are frequently mutated in patient melanoma samples." (PMID 26221190, 2015). "Kiss-1 has been identified as a putative human metastasis suppressor gene in melanomas." (PMID 25111296, 2014). "Notably, INPP4B was found to serve as a tumor suppressor gene in melanoma via regulating PI3K/Akt signaling, which impacts the proliferative, invasive, and tumorigenic capacity of melanoma cells." (PMID 38474285, 2024).
hepatocellular carcinoma (15 papers, 2005 to 2022). A malignant tumor that arises from hepatocytes. "However, DKK4 expression was shown to be associated with decrease in hepatoma cells progression induced by thyroid hormones and has been marked as tumor suppressor gene in hepatocellular carcinoma." (PMID 33346226, 2020). "Our in vitro cell experiment suggested that IDH1 may act as a tumor suppressor gene in hepatocellular carcinoma in that loss-of-function of IDH1 significantly promoted hepatoma cell growth and migration; whereas overexpression of wild-type IDH1 had opposite effects." (PMID 27469031, 2016). "A recent study demonstrated that HAMP, as a tumor suppressor gene of hepatocellular carcinoma, downregulation contributes to proliferation, aggressiveness, and metastasis of hepatocellular carcinoma via the cyclin 4-dependent kinase-1/STAT3 pathway." (PMID 36585741, 2022). "GAS8-AS1 has also been regarded as a putative tumor suppressor gene in papillary thyroid cancer and hepatocellular carcinoma." (PMID 31749921, 2019). "Functional evidence and signaling pathway studies indicate that MCC acts as a tumor suppressor gene by inhibiting the oncogenic NF-κB and β-catenin pathways in CRCs and hepatocellular carcinoma." (PMID 25200342, 2014). "MiR-101 was shown to promote apoptosis and suppress FOS oncogene expression in human hepatoma cells and to act as tumor suppressor gene in carcinogenesis of human hepatoma." (PMID 20444294, 2010). "We identified two miRNAs, 101 and 29c, were induced by TPA and down regulated in human hepatoma tissues suggest that they might play as tumor suppressor gene and in tumor formation of HCC." (PMID 20444294, 2010). "In hepatocellular carcinoma, overexpression of DDX3 was observed in hepatocellular carcinoma and DDX3 was identified as a cellular transforming gene in hepatocarcinogenesis." (PMID 26087195, 2015).
osteosarcoma (12 papers, 2012 to 2023). A usually aggressive malignant bone-forming mesenchymal neoplasm, predominantly affecting adolescents and young adults. "MiR-493 has been proved to play the role of tumor suppressor gene in osteosarcoma and inhibit the cell biological process of osteosarcoma, playing an opposite role with FAM64A." (PMID 32184824, 2020). "In summary, miR-133b expression is significantly decreased in human osteosarcoma samples and is a potential tumor suppressor gene." (PMID 24391788, 2013). "It will be interesting to verify the putative target genes and further investigate the mechanism by which miR-34a functions as a tumor suppressor gene in osteosarcoma." (PMID 22457788, 2012). "Therefore, miR-652 may act as a tumor suppressor gene in osteosarcoma and provide a new target for molecular therapy of osteosarcoma." (PMID 35111226, 2022).
colon cancer (10 papers, 2014 to 2021). "Finally, ARID1A, a chromatin remodeling gene, has also been reported to be mutated in colon cancer." (PMID 26379039, 2015). "ITIH5 is also expressed by normal skin fibroblasts but not by epidermal keratinocytes and is a novel putative tumour suppressor gene in colon cancer." (PMID 30678366, 2019). "However, some studies defined miR-211 as a tumor promoter, by inhibiting the expression of SRC kinase signaling inhibitor 1 (SRCIN1), miR-211 was proved to promote human non-small cell lung cancer, and by targeting tumor suppressive gene CHD 5, miR-211 can promote human colon cancer." (PMID 28924391, 2017). "However, in other instances, DKK1 was found to be repressed in certain colon cancers and it was suggested that DKK1 might act as a tumor suppressor gene." (PMID 26545120, 2015).
leukemia (10 papers, 2010 to 2025). A malignant (clonal) hematologic disorder, involving hematopoietic stem cells and characterized by the presence of primitive or atypical myeloid or lymphoid cells in the bone marrow and the blood. "EVI1 (Ecotropic Viral Integration site I), which was originally identified as a myeloid transforming gene by means of retroviral insertional mutagenesis in mouse leukemia, encodes a nuclear DNA binding zinc finger protein." (PMID 21980434, 2011). "The TAD structural changes involve the vascular endothelial growth factor gene VEGFA, which is a major tumor angiogenic gene that is over-expressed in leukemia (see reviews for more details), consistent with the fact that K562 cells are chronic myelogenous leukemia cells." (PMID 38218905, 2024). "In acute myeloid leukemia (AML), in particular, controversial new findings indicate that HIF-1α can act either as an oncogene or a tumor suppressor gene, and this may depend on the stage of leukemia development and/or the AML sub-type." (PMID 27447550, 2016). "These suggested that PDE4DIP might be a tumor suppressor gene in leukemia." (PMID 32638549, 2020).
acute myeloid leukemia (9 papers, 2006 to 2024). Acute myeloid leukemia (AML) is a group of neoplasms arising from precursor cells committed to the myeloid cell-line differentiation. "Sprouty-related, EVH1 domain-containing protein 1 (SPRED1) has been identified as a novel tumor suppressor gene in acute myeloid leukemia (AML)." (PMID 35359401, 2022). "Mcl-1 is an important antiapoptotic gene, promoting cell survival in various hematological malignancies, including multiple myeloma (MM), acute myeloid leukemia (AML), and NHL." (PMID 34833935, 2021).
non-small cell lung carcinoma (9 papers, 2014 to 2025). A group of at least three distinct histological types of lung cancer, including non-small cell squamous cell carcinoma, adenocarcinoma, and large cell carcinoma. "Hsa-miR-361-3p, downregulated in our study, was reported to act as a tumor suppressor gene in non-small cell lung carcinoma (NSCLC)." (PMID 38326829, 2024). "Low FOXP1 expression has been reported to be associated with poor prognosis in non-small cell lung cancer, while NFAT1 has been reported to act as a tumor suppressor gene." (PMID 26465158, 2015). "In addition TFG has been identified as a putative metastatic melanoma tumour suppressor gene and is also thought to play a role in non-small cell lung cancer, acting as a translocation partner for anaplastic lymphoma kinase (ALK)." (PMID 24999993, 2014). "Its expression has been shown to be downregulated by epigenetic modification in non-small cell lung cancer and hence, RXRG is regarded as a tumor suppressor gene." (PMID 41439026, 2025).